BRCA1 (BRCA1 DNA repair associated)
Diseases named in the same sentence as BRCA1 in open-access papers (continued):
Sharing a sentence is not in itself a finding about the gene and the disease.
cancer (continued). "For instance, reports reveal that PRMT1-mediated BRCA1 and c-Myc methylations can regulate cancer cells cell cycle progression and proliferation." (PMID 34775498, 2021). "Cells expressing BRCA1 cancer variants were more sensitive to MMS and less prone to recombination as compared to cells expressing WT BRCA1." (PMID 34395585, 2021). "One signature is associated with biallelic inactivation of BRCA1 and BRCA2 (due to HR deficiency) but has also been demonstrated in breast and pancreatic cancers from individuals with constitutional PALB2 truncating variants." (PMID 33854214, 2021). "BRCA1/2-driven tumors exhibit chromosomal instability, which results in accumulation of genomic rearrangements and, possibly, emergence of cancer-specific antigens." (PMID 34454564, 2021). "We present a cohort of 9543 unrelated individuals including ones with cancer and unaffected individuals from population of Latvia, who were tested for three most common BRCA1 founder PV." (PMID 33468216, 2021). "Synthetic lethality associated with BRCA1/2 and PARP inhibition is well established and widely used for targeting homologous recombination deficient cancers." (PMID 34067960, 2021). "Boadicea v4 Beta (Centre for Cancer Genetic Epidemiology, 2020) considers BRCA1, BRCA2, PALB2, CHEK2, and ATM mutations in the same cancers." (PMID 34406119, 2021). "Understanding the mechanisms involved in pathway choice for DSB repair is crucial to develop targeted therapeutic interventions in cancer cells, as, for example, is the case of poly-ADP ribose polymerase (PARP) inhibitors in Brca1-deficient cancers." (PMID 33672015, 2021). "Here, we demonstrate that synergistic lethal interactions underpin the mutual exclusivity between oncogene activation and BRCA1/2 abrogation in cancers, and we identify oncogene-mediated transcriptional deregulation as their driving mechanism." (PMID 34389725, 2021). "Sporadic cancers with the BRCAness phenotype generally demonstrate lower sensitivity to BRCA1/2-specific drugs, as compared to hereditary BRCA1/2-driven malignancies." (PMID 34681592, 2021). "Inhibition of ASPM expression promotes HERC2-mediated BRCA1 degradation, compromises HR repair efficiency and chromosome stability, and sensitizes cancer cells to ionizing radiation." (PMID 34142045, 2021). "Three EBSs have been identified in the enhancer region of BRCA1, and EGR1 is able to directly bind to the EBSs and to start BRCA1 gene expression thus initiating DNA repair and inhibiting cancer progression." (PMID 33842351, 2021). "In total, 78 of the 448 (17.4%) families had at least one VEO cancer case (BC and/or OC): 15% of BRCA1 families included a VEO-BC case and 8% a VEO-OC case, with 9% and 2%, respectively, for BRCA2 families." (PMID 34356116, 2021). "In the Korean general population in gnomAD (non-cancer, v.2.1.1, 1887 subjects), 5 different BRCA1 PLPVs in 7 carriers and 6 different BRCA2 PLPVs in 7 carriers were found." (PMID 34063308, 2021). "Nonetheless, the DNA repair activities of BRCA1 are also dependent on its import into the nucleus via two nuclear localization signals (NLS), and cancer-associated mutations often disrupt its nuclear import." (PMID 33879063, 2021). "We collected a total of 335 BRCA variants derived from Taiwanese population, including 164 from general population, 126 from the Taiwanese cancer patient cohort, and 45 (19 in BRCA1 and 26 in BRCA2) from both groups." (PMID 34235180, 2021). "Among these cell lines, in addition to HeLa and MDA-MB-231, 11 cancer cell lines have functional BRCA1 and HR." (PMID 34616682, 2021). "It would be interesting to uncover the mechanism by which MUS81 insufficiency leads to such different phenotypes between BRCA1- and BRCA2-deficient cancer cells." (PMID 33791310, 2021).
cancer (continued). "For instance, the overall response rates to platinum in germline bi-allelic mutant BRCA1/2 cancers range from 65 to 95%." (PMID 34696429, 2021). "With the identification of BRCA1 and BRCA2, their roles in conferring risk for BC and OC in various populations were investigated by targeted gene sequencing analyses of cancer cases." (PMID 34298626, 2021). "In an ongoing trial (ClinicalTrials.gov Identifier: NCT04258280), our goal is to improve cancer genetic counseling outcomes for BRCA1/2-positive mothers and their adolescent and young adult (AYA) children." (PMID 34565430, 2021). "Adverse mental health symptomology is often heightened considering BRCA1/2 diagnoses and what they mean for their health in the future, often compounded if testing is prompted by a cancer diagnosis." (PMID 34969949, 2021). "Thus, BRCA1/2-positive mothers of adolescent and young adult children may benefit from behavioral intervention by their peers–addressing mothers’ unique concerns and questions about ways to communicate hereditary cancer risk information to their offspring." (PMID 34565430, 2021). "The presence of Signature 3 in cases with BRCA1, PALB2 and RAD51C variants, as well as tumor enrichment of these variants, suggest that these cancers are HR-deficient." (PMID 33917078, 2021). "A comprehensive genetic panel, including germline mutations of BRCA1, BRCA2, MMR genes, and other cancer susceptible genes based on family history, should be used to determine appropriate therapy and clinical trial eligibility." (PMID 33947030, 2021). "DDX11 loss greatly sensitizes both BRCA1- and BRCA2-deficient cancer cells to chemotherapeutic drugs, generating more DNA damage and genomic instability." (PMID 33879618, 2021). "Due to elevated cancer risk, RRBSO is recommended at the age of about 35–40 years in BRCA1 and 40–45 years in BRCA2 mutation carriers, whereby family planning and the earliest age at diagnosis in affected family members have to be taken into consideration." (PMID 33885953, 2021). "Following the concept of synthetic lethality, PARPi have gained great relevance, particularly in BRCA1 dysfunctional cancer cells." (PMID 34298653, 2021). "Due to the role of faulty BRCA1/2 in tumorigenesis, BRCA1/2 represents an excellent genetic predictor of cancer and a powerful target for anticancer therapeutics." (PMID 33391401, 2021). "Cyclin D1 overexpression leads to elevated cancer growth and negatively affects functions of proteins involved in DNA repair including BRCA1/2." (PMID 34677582, 2021). "The frequency of germline BRCA1/2 gene mutation carriers and the ratio of germline BRCA1 to BRCA2 mutations in BRCA-related cancer patients vary depending on the population." (PMID 34356066, 2021). "We tested for only BRCA1 and BRCA2 in the phase 1 of the project, but we are revising our policy to include other cancer susceptibility genes as well." (PMID 33920818, 2021). "Lymph node stage, tumor stage, age, metastasis score, tumor size, specific cancer type, sex, and race showed some noteworthy differences across BRCA1 mRNA-low versus -high groups." (PMID 34611475, 2021). "For example, germline mutations in BRCA1 and BRCA2 can increase the risk of developing many cancers with genomic instability, particularly breast and ovarian cancers." (PMID 34830134, 2021). "Perturbations of BRCA1 function can act as a potent driver of cancer progression and can impact therapeutic responses to chemotherapies including platinum drugs and PARP inhibitors." (PMID 34659365, 2021). "For example, cancer cells with low expression of BRCA1 are sensitive to DNA-damaging agents, such as cisplatin, but are resistant to spindle poisons, such as taxol." (PMID 34068585, 2021).
cancer (continued). "It turned out that BRCA1 and BRCA2 are quite exceptional in their high penetrance, with most cancer predisposition genes showing only mild effects." (PMID 34290314, 2021). "The lowest detection rate overall both for BRCA1/2 and additional panel genes was for grade 1 cancers with 4.1% and 4.5% respectively." (PMID 34439310, 2021). "PARPi is an effective therapeutic agent against BRCA1- and BRCA2-associated cancers, as BRCA mutations lead to DNA double-strand breaks that cannot be efficiently repaired, thus leading to the death of cancer cells." (PMID 33609766, 2021). "In adult cells, DNA methylation has been extensively demonstrated to be involved in the onset and progression of cancer, mainly through the silencing of tumor suppressor genes such as BRCA1, ATM, and PALB2." (PMID 33808555, 2021). "However, additional studies are needed to elucidate the mechanisms by which BRCA1 controls the expression of several major regulators of actin cytoskeleton and cell adhesion, and to uncover the driving forces underlying migration and metastatic phenotypes of BRCA1-mutated cancer cells." (PMID 35008272, 2021). "We used the BC PanCancer Atlas and CRC Firehose Legacy databases, and using the cBioPortal co-expression tool identified the top 100 genes which correlated with BRCA1 mRNA expression in each cancer type." (PMID 34611475, 2021). "It maps on the centromeric region of BRCA1 on 17q21 chromosome which is responsible for 75%, 50%, and 40% deletion in many cancers like ovarian, breast, and prostate cancers, respectively." (PMID 33628386, 2021). "While such cancer cells subsequently show cell death, the normal cells, which have normal BRCA1 and BRCA2 tumor suppressor genes, carry out homologous recombination repair and escape death." (PMID 34070839, 2021). "Because cfDNA is a mixture of DNA originating from practically all regenerating tissues in the body, our data on a group of elderly, cancer‐free, healthy women strongly suggest that hypermethylation of the BRCA1 promoter only occurs in (pre‐) cancerous cells." (PMID 34601813, 2021). "Failure to correct DNA damage in DNA repair defective cells, such as in BRCA1 and BRCA2 mutated backgrounds, is directly associated with increased cancer risk." (PMID 34830134, 2021). "BRCA1 is frequently dysfunctional in human breast, ovarian, pancreatic, among other cancers, contributing to the accumulation of genomic defects." (PMID 34298653, 2021). "Taken together, the current data suggests the involvement of BRCA1/2 in neovascularization and cancer progression." (PMID 35008272, 2021). "On the other hand, POPA was the best augmenter of the PARP1/ACTB mRNA ratio in BRCA1-null UWB1.289 cancer cells." (PMID 34440232, 2021). "The prime example of this is the use of PARP inhibitors in BRCA1 mutant cancers, which is now an approved targeted therapy in several cancers." (PMID 34764236, 2021). "The global importance of such rare variants in tumorigenesis has been addressed by pan-cancer analysis, revealing significant enrichments for protein truncating variants in genes such as ATM, BRCA1/2, BRIP1, and MSH6." (PMID 33809641, 2021). "Heterozygous carriers of germline pathogenic variants in either BRCA1 or BRCA2 are at significantly increased lifetime risk of breast and other cancers, with risk accruing from a young age." (PMID 34771713, 2021). "Relative to BRCA1 and BRCA2, less is known of the role of BRIP1 and CHEK2 cancer predisposing genes in conferring risk of BC and OC in FCs." (PMID 34298626, 2021). "Alterations of ATM and BRCA1 gene expression are found in cancers, some of which are correlated with treatment response and patient outcome." (PMID 34068585, 2021). "Comprehensive cancer panel testing revealed pathogenic variants in cancer genes other than BRCA1 and BRCA2, suggesting that testing only BRCA1 and BRCA2 would have missed 8 out of 44 suspected HBOC patients (18%)." (PMID 33558524, 2021).
cancer (continued). "Even in the setting of inherited germline mutated BRCA1 or BRCA2, which is present in all the cells of the breast, only solitary cancers or at most multifocal cancers limited to 2 or 3 foci arise." (PMID 34044885, 2021). "BRCA1-null UWB1.289 cancer cells transcribe a significantly higher PARP2 (t-test, p < 0.001) and a strikingly lower PARP1 mRNA content (t-test, p < 0.001) due to the BRCA1 loss of activity." (PMID 34440232, 2021). "Regarding specific cancer-associated genes, the CYT-high subgroup had more CNAs, including gains in NF1, CDK12, ERBB2, RARA, MDM4 and MYC; and losses in BRCA1, CD274 and APC." (PMID 34316699, 2021). "Predictors of bilateral mastectomy as the first surgical procedure were younger age, bilateral cancer, BRCA1/2-positive results, and preoperative genetic testing." (PMID 33996049, 2021). "The activity of PARP inhibitors in patients with BRCA1 or BRCA2 mutant cancers was the first clinical demonstration of synthetic lethality for cancer therapy." (PMID 33578789, 2021). "Mitoxantrone and doxorubicin preferentially killed the HR-deficient cancer cell lines, HCC1937, UWB1.289, and PE01 compared to their HR-proficient counterparts, HCC1937+BRCA1, UWB1.289+BRCA1, and PE01C4-2, respectively." (PMID 33784323, 2021). "Poly-adenosyldiphosphate-ribose polymerase (PARP) inhibitors are a relatively new type of cancer treatment initially designed to target HRR defects, especially for people with inherited mutations in BRCA1/2." (PMID 33407429, 2021). "Contrarily, on the other hand, hypoxia reduces the expression of several key HRR effectors such as NBN, MRE11, RAD51, and BRCA1 in different cancer cell models." (PMID 34539584, 2021). "Research has focused on expanding the benefit of PARP inhibitors to wild-type BRCA1 cancer cells by combining PARP inhibitors with other treatment options in order to achieve a synthetic lethal effect." (PMID 34207158, 2021). "POLQ was revealed to be synthetic lethal with DNA repair genes frequently mutated in cancer (such as ATM, ATR, BRCA1/2, FANCD2, Ku70, RAD52, RAD51C, TP53BP1) and extensive efforts for the development of Polθ inhibitors are made by several companies." (PMID 34201502, 2021). "In human cells, satellite DNA overexpression is observed during stress, senescence, aging, and in various cancers associated with deregulation of epigenetic enzyme activities (e.g., DNMT3B, KDM2A, JMJD2B, SIRT6, GCN5, BRCA1, PRC1, and PRC2)." (PMID 34681626, 2021). "Germline and somatic mutations across (i.e., MMR versus HR) and within (i.e., BRCA1 versus BRCA2) DDR pathways showed variable associations with TMB, neoantigen loads, and indel neoantigen hotspots in a cancer-dependent manner." (PMID 34095878, 2021). "Consistently, restoration of miR‐223 (3p) in BRCA1, BAP1‐deficient cancer cells is synthetic lethal, probably due to repression of NHEJ components." (PMID 32954644, 2021). "Seven kinds of RAD52i have been proposed, and some of these compounds are approved by the FDA, indicating that RAD52i is an attractive approach for BRCA1-, BRCA2-, RAD51 paralog-, and PALB2-deficient cancer." (PMID 33922657, 2021). "These clinical findings, consistent with our results in mice, further confirm that BRCA1 suppresses the PDGFRβ-PKCα signaling pathway in breast basal-like cancer development and progression." (PMID 33478572, 2021).
cancer (continued). "There is evidence that BRCA1 modifies estrogen-mediated tumor progression, as increased E2-ER signal accelerate preneoplasia and cancer development in the absences of BRCA1, favoring breast de-differentiation and tumorigenesis." (PMID 33869016, 2021). "We found that 60% of the cancer patients exhibited BRCA1 promoter hypermethylation at one point, although 24% lost hypermethylation during treatment." (PMID 34601813, 2021). "Over the past 25 years since the discovery of BRCA1 and BRCA2, it is increasingly clear that FCs of Quebec, Canada have played a significant role in defining the genetic landscape of cancer predisposing genes." (PMID 34298626, 2021). "For instance, BRCA1 and BRCA2 show significant global variations according to contribution in regional cancer incidence and to mutation spectrum." (PMID 33827469, 2021). "This review aims to emphasize the potentiality of the DDR pathways, particularly of BRCA1 and interconnected molecules, in precision cancer therapy." (PMID 34298653, 2021). "The presence of BRCA1-2 PVs can also impact cancer treatment decisions, principally with regard to the employment of platinum agents or poly(ADP-ribose) polymerase (PARP) inhibitors." (PMID 34026625, 2021). "In this analysis, we only considered genes that were affected in at least four TCGA cases within a cancer type and therefore only seven genes (BRCA1/2, ATM, ATR, PALB2, CHEK2, BRIP1) were included." (PMID 34572800, 2021). "Our results elucidate how RNF19A-mediated ubiquitylation of BARD1 induces dissociation of BRCA1, unmasks the NES region of BARD1, restrains HR activity, and makes cancer cells more susceptible to PARPi treatment." (PMID 34789768, 2021). "Evidence supports that the predicted neo‐antigen load is higher in BRCA1‐ and BRCA2‐mutant and HR‐deficient cancers, owing to the theory that impaired DDR leads to genetic alterations and putative neo‐antigens, thus favoring recognition by the immune system." (PMID 33811746, 2021). "Pathogenic BRCA1 and BRCA2 variants have been reported in 65–85% of cancer syndromes featuring high-grade serous ovarian carcinoma (HGSC), the most common histopathological subtype of epithelial OC, and in 10–20% of HGSC cases regardless of age at diagnosis." (PMID 34861889, 2021). "The discovery of synthetic lethal interaction between breast cancer susceptibility gene 1/2 (BRCA1/2) tumor suppressors and poly ADP-ribose polymerase (PARP) DNA repair protein provided an opportunity to use PARP inhibitors in clinical cancer therapy." (PMID 34359636, 2021). "For instance, poly (adenosine diphosphate-ribose) polymerase 1 (PARP1) and breast cancer 1 (BRCA1) are a famous SL gene pair, leading to the first clinically approved SL-based cancer drug, PARP inhibitor." (PMID 34252965, 2021). "Expression of known cancer related missense mutant BRCA1 (e.g. A1789T or M1775R) leads to an increased HR and thereby the frequency of recombination of the two truncated HIS3 alleles is increased compared to WT." (PMID 34395585, 2021). "Given the unique genetic architecture of the FC population of Quebec, it is likely that carriers of FANCI c.1813C>T have common ancestors as has been shown with carriers of frequently occurring pathogenic variants in BRCA1, BRCA2, and MSH6 in cancer families." (PMID 34861889, 2021). "In the majority of health systems, the access to genetic testing depends on a family-history model; thus, the detection of BRCA1/2 carriers before a cancer diagnosis remains limited." (PMID 34503502, 2021). "Compared to patients without CPGs, distinct clinical phenotypes including the onset age, family and personal cancer history, and pathological features have been found in patients with BRCA1, BRCA2, and other CPGs." (PMID 34336698, 2021).